CYP1B1 (cytochrome P450 family 1 subfamily B member 1)
Diseases named in the same sentence as CYP1B1 in open-access papers (continued):
Sharing a sentence is not in itself a finding about the gene and the disease.
cancer (continued). "However, the molecular and clinical characteristics of the melatonergic metabolic enzyme CYP1B1 in cancer still remain unknown." (PMID 36428734, 2022). "Importantly, we will discuss how CYP1B1-mediated signaling pathways may have divergent effects of the cardiovascular tissues and the cancer." (PMID 33185690, 2020). "In parallel, we will also discuss the role of CYP1B1 inhibitors in preventing resistance to cancer treatments to highlight that CYP1B1 inhibition may not only prevent cardiovascular toxicity, but also augment the anti-cancer effects of different cancer treatments." (PMID 33185690, 2020). "As suggested earlier, our observations may indicate that demethylation and upregulation of CYP1B1 in the oral mucosal tissues of smokers is not causal for the development of cancer, but in contrast, part of the normal cellular detoxification." (PMID 31331382, 2019). "Therefore, it may be possible that CYP1B1 is involved in docetaxel resistance through diverse mechanisms in each different type of cancer." (PMID 25860934, 2015). "Finally, miR-27b regulates CYP1B1 expression post-transcriptionally in cancer tissues." (PMID 24966868, 2014). "Thus CYP1A1 and CYP1B1 play essential roles in cancer therapeutics, as well as carcinogenesis." (PMID 24358191, 2013). "This suggests that CYP1B1 could activate anticancer agents specifically in the cancer cells." (PMID 23873331, 2013). "Furthermore, decreased availability of CYP1B1 enzyme leads to a lesser activation of PAH to reactive metabolites which otherwise could cause DNA damage and cancer development." (PMID 19835593, 2009). "Specifically, cytochrome P450 1B1 (CYP1B1), which hydroxylates estrogen, contributes to cancer initiation through procarcinogen metabolism." (PMID 41249771, 2025). "Conversely, some CYP450 enzymes, like CYP1A1, CYP1A2, CYP1B1, CYP2A6, and CYP2E1, have a role in the onset and development of many cancers by converting pro-carcinogenic substrates into carcinogens." (PMID 39062040, 2024). "A PROTAC strategy was actually used to degrade extrahepatic cytochrome P450 1B1 (CYP1B1), which is highly expressed in various tumors, for cancer prevention, therapy, and reversal of drug resistance." (PMID 38755248, 2024). "CYP1B1 and CYP4B1 are involved in the tumorigenicity of different cancers, like ovarian, breast, and prostate." (PMID 39062040, 2024). "To evaluate the clinical relevance of CYP1B1 and ACSL4 in CRC tumors, we first compared the expression of CYP1B1 and ACSL4 in CRC cancer tissues and adjacent normal tissues." (PMID 37059712, 2023). "In cancer cell studies, SP1 was considered a key mediator of CYP1B1 action, whilst CYP1B1 was shown to activate a epithelial to mesenchymal transition and Wnt/beta-catenin-signaling pathways, upregulating beta-catenin and other TFs, such as ZEB2 and SNAI1." (PMID 37511270, 2023). "This panel included proteins associated with EMT induction (Vimentin-pSer56, NFκB p100/p52 and IKKε-pSer172) or drug metabolism (CYP1B1), which are also known to induce drug resistance to DTX and PTX in cancer cells." (PMID 37596623, 2023). "The overexpression of CYP1B1 and CYP2A7 in different cancers is related to increased resistance to different chemotherapeutic agents." (PMID 36077660, 2022). "Overexpression of AhR in many cancers triggers production of toxic metabolites via overexpression of CYP1A1 and CYP1B1." (PMID 36160406, 2022). "CYP1B1 is considered to be an important modulator of FAM and a potential therapeutic target in cancer therapy because of its ability to activate procarcinogens." (PMID 36505493, 2022). "Previous studies showed that silencing of cyp1b1 in mice inhibits the metabolism of 7,12-dimethylbenz[a]anthracene (DMBA), and reduced the incidence rate of DMBA-induced malignancies." (PMID 35887201, 2022). "In this model, expression of CYP1B1 is viewed as a surrogate or biomarker of AHR signaling and hence the activity of this cancer progression circuit." (PMID 36077068, 2022).
cancer (continued). "The aim of this work is to determine the frequency of Single Nucleotide Polymorphisms (SNPs) in CYP1A1 (rs1048943, Ile462VaI and rs4646903/MSP1) and CYP1B1 (rs1056836, Leu432Val) genes in patients with CRC cancer." (PMID 33906313, 2021). "We found all expression-validated cancer and migration-related genes had at least one putative DRE(s) in their promoters, especially CYP1B1, ID1, and SDC1, which had 8, 5, and 6 putative DRE sites, respectively." (PMID 34955744, 2021). "Among them, six melatonergic genes were significant unfavorable factors in cancers (e.g., MTNR1A in ESCA and LIHC; GPR50 in KIRC, LIHC, and STAD; NQO2 in BRCA, LIHC, and LUSC; CYP1B1 in KIRC and STAD; ASMT in ESCA, HNSC, and LUAD; and MTNR1B in STAD)." (PMID 33842355, 2021). "These qPCR results confirmed a similar distribution of gene expression; overexpression of CYP1B1, CYP7A1, CYP17A1, and CYP19A1, and repression of CYP1A2, CYP2B6, CYP2C19, and CYP26A1 was observed in cancer tissues." (PMID 31258835, 2019). "In particular, the mammosphere (CSCs) of all cancer cells tested, with the exception of MDA-MB231, showed higher CYP1A1 mRNA levels than CYP1B1." (PMID 28103884, 2017). "Mmu-miR-505-5p was downregulated in Sca-1+CD31− compared to Sca-1+CD31+ cells, with targets Cyp1b1, Dcbld2, Igf1, and Ppp1r14b,Txndc5 increased in expression; Igf1 was involved in mTOR and PI3K-Akt signaling and Cyp1b1by with microRNAs in cancer." (PMID 27298624, 2016). "CYP1B1 and CYP1A1 have also been proposed as targets for cancer chemotherapy for their differential and selective overexpression in tumour cells." (PMID 18454852, 2008). "Also, the expression of PDGF‐bb, which is a promoter of cancer cell proliferation, was significantly reduced by suppression of ADAM12 and CYP1B1 in obese‐derived adipocytes." (PMID 39806854, 2025). "This aligns with our drug sensitivity analysis, which demonstrated mild positive (resistance) and negative (response) correlations between CYP1B1 expression and various drugs across pan-cancer GDSC datasets." (PMID 41155673, 2025). "Similarly, it was noted that CYP1B1 plays a key role in the metabolic activation of different environmental procarcinogens, suggesting that it may contribute to the maintenance of the homeostasis xenobiotic metabolism and as such, it can be of key relevance for cancer formation." (PMID 39806854, 2025). "Expression and functional role of AhR, CYP1A1 and CYP1B1: Animal and clinical data provide evidence for the role of AhR in gastric tumorigenesis, implicating the receptor in the regulation of tumor growth, EMT, migration, invasion, and cancer aggression." (PMID 39200369, 2024). "In summary, our findings illuminate the vulnerability of cancer patients to drug resistance, which is particularly evident in the increased expression of ABCB1 and CYP1B1 in tumor samples from the poor-responders category, along with the associated molecular pathways." (PMID 38534761, 2024). "This heterodimer targets downstream target genes, activating the corresponding genes' abnormal expression, such as cytochrome P450 1A1/ cytochrome P450 1B1 (CYP1A1/CYP1B1), ultimately leading to cell toxicity, interference with animal endocrine, immunotoxicity, and even occurrence of cancer." (PMID 36829212, 2023). "This feature can be used in cancer therapy with prodrugs activated by CYP1A1 and CYP1B1." (PMID 37511239, 2023). "Overall, CYP1B1, NTRK1, and NFATC2 are not related to cancer risk but have potential roles as prognostic markers and actionable drug targets." (PMID 37628631, 2023). "Notably, CYP1B1, CYP2W1, CYP2J2, and, more recently, CYP4Z1 have been determined to have cancer-specific expression." (PMID 38001897, 2023). "As to whether the AhR-induced CYP1B1 leads to the ‘backward’ conversion of melatonin to NAS, with released NAS activating TrkB on cancer cells and cancer stem-like cells will be important to determine." (PMID 36613754, 2022).
cancer (continued). "The fact that CYP1B1 is overexpressed in many types of cancers but is either found in at minute levels or absent in normal tissues makes it a promising therapeutic target." (PMID 34636736, 2021). "As would be expected, high AHR expression and activity was usually, although not always, correlated with up-regulated CYP1A1 and/or CYP1B1 in cancers of the GI tract, bladder, head and neck, and breast." (PMID 33396563, 2020). "Importantly, the AHR is also constitutively active and overexpressed in many types of cancer, and CYP1A1 and CYP1B1 are overexpressed in many cancers." (PMID 32398692, 2020). "Because expression of CYP1B1 is elevated in various cancers, but not in normal tissues, it is a potential therapeutic target." (PMID 31775380, 2019). "Interestingly, MCF-7 mammosphere cells showed the highest expression levels of CYP1A1 (27-fold) and CYP1B1 (7-fold) than corresponding adherent cells among all cancer cells, followed by T47D (20-fold for CYP1A1 and 4-fold for CYP1B1)." (PMID 28103884, 2017). "In contrast, there is no obvious difference in CYP1B1 mRNA levels between cancer and normal tissues, suggesting that its expression is regulated at the post-transcriptional level." (PMID 25860934, 2015). "Human studies have suggested that high levels of CYP1B1 expression and low levels of COMT expression in adjacent non-tumour tissue were associated with an increased risk of BC and other E2-responsive cancers." (PMID 24629213, 2014). "Differential expression of CYP1A1 and CYP1B1 in various tumor types, compared to normal tissue has been demonstrated by several studies, thus highlighting the potential use of the two CYP1 isoforms in cancer prognosis." (PMID 24358191, 2013). "The CYP1B1 mRNA level was very low (RA = 0.05 ± 0.01) while CYP1B1 protein was not present in colorectal LOVO cancer cells." (PMID 23873331, 2013). "The remaining CYP1B1 SNP, rs2855658, is located in a seed microRNA region, but has no previously established links to cancer." (PMID 23637977, 2013). "Such inhibitors are thought to be potential anti-carcinogens if they could inhibit the activities of CYP1B1 and CYP1A1 to metabolize PAHs to toxic intermediates and/or decrease their ability to detoxify cancer drugs." (PMID 22686946, 2012). "Thus, not only ADAM12 and CYP1B1 can be seen as prognostic markers in RCC, but we also propose that interfering with the identified genes as well as hampering adiposity is an unmet adjuvant strategy in cancer therapy." (PMID 39806854, 2025). "Therefore, induction of the expression CYP1B1 by Uro-B is not a desirable effect required in cancer therapy." (PMID 34164422, 2021). "In this review, we discuss the growing body of evidence suggesting that inhibition of the cytochrome P450 1B1 enzyme (CYP1B1) can be a promising therapeutic strategy that has the potential to prevent cancer treatment-induced cardiovascular complications without reducing their anti-cancer effects." (PMID 33185690, 2020). "The exact mechanisms of CYP1B1 overexpression in cancer cells and tumors are not fully elucidated." (PMID 33185690, 2020). "CYP1B1 is overexpressed in various types of human cancers, but not in healthy tissues." (PMID 31775380, 2019). "RES can inhibit activating enzymes such as CYP19 (aromatase) and CYP1B1 (a kind of cytochrome P450 enzyme), and induce the expression of detoxification enzyme of NQO1 (NAD(P)H:quinone oxidoreductase 1), thus blocking the formation of estrogen-DNA adducts to protect against estrogen-initiated cancer." (PMID 30687096, 2018). "To explore the role of CYP1B1 in cancer progression, we investigated the action of CYP1B1 in cells with increased CYP1B1 via the inducer 7,12-dimethylbenz[α]anthracene (DMBA) or an overexpression vector, in addition to decreased CYP1B1 via the inhibitor tetramethoxystilbene (TMS) or siRNA knockdown." (PMID 26981862, 2016).
cancer (continued). "Second, blocking the activity of CYP1B1 may reduce the accumulation of carcinogenic substances, including those related to estrogen, and this alteration may function in concert with PTX to slow the growth of the cancer cells." (PMID 25516145, 2015). "It is not entirely clear whether the inhibition of CYP1B1 by itself has the potential ability to induce the apoptosis of cancer cells; this requires further investigation." (PMID 25516145, 2015). "Additionally, CYP1B1 may induce epithelial-mesenchymal transition (EMT) and activate the Wnt/β-catenin signaling pathway, both of which contribute to the progression of the carcinoma." (PMID 40303287, 2025). "However, the data presented here and by others support the idea that CYP1B1 directly contributes to complex cancer phenotypes including chemoresistance that may not directly involve drug metabolism." (PMID 36077068, 2022). "A number of the genes identified have been induced in normal human cells by BaP (e.g. CYP1B1 and NQO1) and this gives promise that the expression changes we are observing in these two cell systems are not likely to be artefacts of their cancer phenotype." (PMID 17042939, 2006). "Unlike CYP1B1 and CYP2E1—two other notable P450 enzymes that, while expressed in various cancers, including pediatric STSs, are also present in corresponding normal tissues—CYP2W1 appears to be exclusively upregulated in tumor tissues, making it a uniquely selective therapeutic target." (PMID 40136335, 2025). "However, since some tumors have relatively normal gene expression level and there is interindividual variability in samples, the differences in CYP1B1 and CYP7A1 expression levels between normal and cancer tissues were not considered statistically significative." (PMID 31258835, 2019).
tumor (159 papers, 2001 to 2026). "This retrospective analysis of pretreatment TNBC core biopsies found that elevation of CYP1B1, a drug-metabolizing enzyme in tumor cells, was associated with resistance to NAC in patients with TNBC treated initially with doxorubicin." (PMID 40478625, 2025). "In our study, we observed a significant association between CYP1B1 expression and tumor M stage, as well as poor prognosis in ccRCC patients." (PMID 38184608, 2024). "Collectively, these results demonstrated that VitA+ or VitA-Lrat+Fbln2+ aHSC was a unique tumor-associated aHSC subpopulation which likely produced 12-HHTrE by CYP1B1." (PMID 37156770, 2023). "This confirmed the wide expression of CYP1B1 in tumor tissues by tARPC as a response to the damage caused by cisplatin." (PMID 37371125, 2023). "Tumor expression of CYP1B1 was inversely associated with CLDN7 expression, and CYP1B1HI/CLDN7LOW identified patients with lower median survival." (PMID 36077068, 2022). "Our results identified that the dysregulated expression of CYP1B1 was associated with the clinical stage, tumor grade, immune cell infiltration, TMB, MSI, neoantigen, activation of multiple melatonergic and immune-related pathways, and therapeutic resistance." (PMID 36428734, 2022). "CYP1B1 was significantly associated with tumor purity (r= −0.197, P = 9.53e−04), B cells (r = 0.164, P= 3.81e−03), CD4 + T cells (r = 0.121, P = 4.43e−02), and dendritic cells (r= 0.119, P = 4.88e−02)." (PMID 34784845, 2021). "There were significant associations between CYP1B1 expression and tumor pathological subtype (P=.01), tumor grade (P=.03), lymph node metastasis (P=.01), and HPV 16/18 expression (P=.04)." (PMID 34636736, 2021). "Does the increased YY1 in tumours associate with heightened levels of CYP1B1, mGluR5, P2Y1, O-demethylation and CYP2C19, and thereby with the “backward” conversion of melatonin to NAS and TrkB-driven GSC, survival and proliferation?" (PMID 35582450, 2020). "In vivo, tumours expressing the variant CYP1B1 had higher growth rates and were markedly drug-resistant." (PMID 32565541, 2020). "Here, using GEO datasets, we showed that the expression of CYP1A1, CYP1A2, and CYP1B1 was associated with grade, stage, and tumor progression in BC patients." (PMID 32907554, 2020). "It must be underlined that the CYP1B1 variation studied is a polymorphism present both in patients’ germline and tumour DNA." (PMID 32565541, 2020). "After a follow-up period of 5 years, it was found that CYP1B1 G119T mutant genotypes were related to a higher risk of tumor recurrence and death after surgical resection." (PMID 28377924, 2017). "Like the seed microRNA and missense mutation SNPs in CYP1B1 that were strongly associated with tumor mutations in the present study, some of the identified RAD23B and ERCC2 SNPs also have potentially functional roles." (PMID 23637977, 2013). "In this small, yet novel, case-only study of genetic risk factors for GIST tumor subtypes we identified several variants in CYP1B1, RAD23B, GSTM1, and ERCC2 that we believe are worthy of further investigation." (PMID 23637977, 2013). "This genotype is known to encode higher CYP1B1 activity and it is believed to contribute to low levels of the ER in these tumours by a reduction in estradiol." (PMID 18797454, 2008). "In GC, CYP1B1 expression was observed to increase with tumor stage and grade, and it was highly correlated with tumor-related fibroblast numbers, immunological checkpoints, microsatellite instability, tumor mutation burden (TMB), and neoantigens." (PMID 40989158, 2025). "We identified that the dysregulated expression of CYP1B1 was associated with clinical characteristics and a tumor immune microenvironment, which may provide a promising predictor and molecular target for clinical immune treatment." (PMID 36428734, 2022). "In addition, overexpression of CYP1B1 has been associated with increased tumor size, increased tumor grade, frequent lymph node metastases and lymphovascular invasion." (PMID 36085146, 2022).